RHOA (ras homolog family member A)
Diseases named in the same sentence as RHOA in open-access papers (continued):
Sharing a sentence is not in itself a finding about the gene and the disease.
tumor (continued). "RhoA overexpression has been observed in various cancers and RhoA activity has been implicated in tumorigenesis and tumor cell invasion." (PMID 30514953, 2018). "In vertebrates, the expression level of RhoA is much higher in tumor cells than in normal cells, indicating a close association with tumor progression." (PMID 30233567, 2018). "There were also indications that these active mutants of RhoA and Rac1 can cause tumor growth in nude mice." (PMID 30544828, 2018). "Rho-associated kinases (ROCKs), which are key downstream effectors of RhoA, have been implicated in tumour motility, invasion and growth." (PMID 29867097, 2018). "Another whole genome sequencing effort of patients with adult T-cell leukemia/lymphoma resulted in the identification of a number of novel point mutations in the RhoA gene in 15% of the tumor material." (PMID 30544828, 2018). "Aberrant RhoA signaling during inactivation of Dlc1 has been shown to cause tumor growth and metastasis." (PMID 28358928, 2017). "The allele frequencies of the G17V RHOA mutations in the dissected PD1+ cells were substantially higher than those in the matched whole tumor samples in 7 of the 10 cases." (PMID 28157189, 2017). "Second, RHOA mutation has been reported to be an early event in carcinogenesis, suggesting that tumor cells harbor the mutation at the early stage in the mucosa." (PMID 25823974, 2016). "In light of the previous reports that RhoA is associated with tumor cell motility and invasion in various types of cancers, we performed a histological review with a particular focus on the association between the RHOA mutation and growth patterns." (PMID 25823974, 2016). "Aberrant Ras/Raf/MEK/ERK or RhoA/cdc42/MLKs/MKK/JNK cascades have been implicated in many types of diseases such as tumor formation and neurodegenerative diseases." (PMID 26734995, 2016). "RhoA is shown to be expressed at the tumor front and found to be associated with poor prognosis in prostate cancer." (PMID 27597870, 2016). "In three-dimensional cultures, mutated RHOA has been associated with an ability to promote escape from anoikis and to facilitate tumor growth, thereby implicating RHOA as an oncogenic driver of diffuse-type GC progression." (PMID 26267324, 2015). "Over-expression of RhoA, RhoB and Cdc42 in the tumours was found to be associated with the presence of lymph node metastases (P = 0.024, P = 0.004 and P = 0.047, respectively)." (PMID 23420497, 2013). "Taken together, these data suggest that Cdc42, Rac1 and RhoA are all closely associated with the invasion and metastasis of tumor cells through regulating the formation of invadopodia." (PMID 23538840, 2013). "Perturbation of Cdc42, Rac1 and RhoA activity results in the loss of normal physiological function and can be related to the pathological conditions, including cellular transformation, tumor invasion and metastasis." (PMID 23538840, 2013). "We also found that P61A6 treatment of H358 tumor xenografts growing in nude mice reduced their growth as well as the membrane association of RhoA in the tumors." (PMID 23607551, 2013). "RhoA, Rac1, and Cdc42 have each been implicated in tumor motility and invasion, are downstream effectors of both LPA1 and S1P1, and therefore were candidates for targeting." (PMID 17156449, 2006). "Aberrant activation of RHOA is associated with tumor progression." (PMID 41291745, 2025). "Increased RHOA expression was found to be associated with advanced tumor stages." (PMID 40600795, 2025). "In tumour tissues with stable silencing of circKIAA1797, the expression levels of the proliferation-associated protein Ki67, the cycle-associated protein Cyclin D1, the migration-associated protein RhoA and the apoptosis-associated protein Bcl2 were reduced." (PMID 40176113, 2025). "Furthermore, the impact of TET2 mutations on non-tumor cells was assessed by calculating the ratio of VAFs between TET2 and RHOA mutations as an indicator of the expansion of TET2-mutated non-tumor cells." (PMID 40164718, 2025).
tumor (continued). "Notably, an IDH2 or RHOA variant detected in the initial pre-treatment tumour sample was detectable in subsequent ctDNA monitoring in all of these patients following relapse." (PMID 40724970, 2025). "Neutrophils secrete anterior gradient‐2 into the extracellular compartment, which increases xCT activity within metastatic tumor cells in a CD98c‐dependent manner, thereby activating the Ras homolog family member A/Rho‐associated protein kinase 2 (RhoA/ROCK2) signaling cascade." (PMID 40027151, 2025). "RhoA‐ROCK‐LIMK2 signaling pathway is associated with autophagy in tumor cells." (PMID 38800967, 2024). "RHOA, a member of the Rho family of small GTPases40, could promote the reorganization of actin cytoskeleton and was associated with tumor cell proliferation and metastasis." (PMID 38413612, 2024). "Moreover, mutations on RhoA that favored immunosuppressive ambience in tumor microenvironment have been recently described." (PMID 38343633, 2024). "Although these studies show that RHOA might be implicated in the malignant transformation of solid tumors, recent evidence has demonstrated its tumor suppressor activity in some hematological malignancies." (PMID 36766776, 2023). "Of the members of this signaling pathway, the APC, AXIN1, TCF7L2, and RHOA genes are most frequently mutated, the latter encoding a low-molecular-mass protein that contributes to cell invasiveness, adhesion, migration, and polarization, and tumor metastasis." (PMID 37509254, 2023). "High-throughput sequencing technologies have identified several gain- and loss-of-function hotspot mutations within the RHOA gene, suggesting, once again, that the GTPase may have tumor-specific functions." (PMID 36766776, 2023). "Additionally, ezrin phosphorylation downstream of RhoA signaling also causes an increase in tumor MV shedding." (PMID 37760395, 2023). "Particularly, mutations in the ARHGAP31 gene could result in enhanced RhoA GTPase activity, which might encourage tumour development and metastasis." (PMID 37927751, 2023). "Although TET-2 mutations are considered secondary events in nMTCL-TFH-phenotype, different studies demonstrate an association of TET-2 and RhoA G17V mutations in these neoplasms, suggesting a biological cooperation between both mutations to promote AITL development." (PMID 37182145, 2023). "Recent cancer genome-wide sequencing studies have unveiled both RHOA gain and loss-of-function mutations in primary leukemia/lymphoma, suggesting that this GTPase may exert tumor-promoting or tumor-suppressive functions depending on the cellular context." (PMID 36766776, 2023). "Thus, the recurrent and dominant negative nature of RHOA mutations in AITL, PTCL, BL and DLBCL strongly support a tumor suppressive role for RHOA in hematological cancers." (PMID 36766776, 2023). "Previous studies have shown that RhoA activity could contribute to the therapeutic effects of MLN by blocking tumor-associated angiogenesis." (PMID 35354476, 2022). "We speculate that mesothelial cells progress to epithelioid MM during EMT, biphasic MM during tumour progression, and sarcomatoid tumours at later stages in parallel with loss of RhoA and vigilin expression." (PMID 36323745, 2022). "Multivariate analysis confirmed that ARHGAP25, RhoA expression, VM, tumor size, TNM stage, and LNM were closely associated with OS and DFS and may be employed as independent prognostic markers of NSCLC." (PMID 36207695, 2022). "ARHGAP25 and RhoA expression is associated with VM and may be of potential value in predicting tumor metastasis, prognosis, and targeted therapy." (PMID 36207695, 2022). "Importantly, heterozygous RhoA deletion significantly inhibited tumor growth, which was associated with tumor-infiltrating Treg cell plasticity and increased tumor-infiltrating effector T cells." (PMID 34721389, 2021). "WT RhoA acts as a tumor suppressor while the mutated G17V RhoA loses this activity." (PMID 33801781, 2021).
tumor (continued). "Indeed, Rac1 is linked with tumor cell migration, while RhoA is associated with tumor growth and metastasis formation." (PMID 33671551, 2021). "Thus, our findings indicate that the loss of GDF15 expression and reduced RhoA activity resulting from loss of TK1 via shRNA silencing leads to reduced tumor and metastatic activity in LUAD cells." (PMID 31589613, 2019). "Activation of ARHGAP35 causes RhoA inactivation and inhibits cell invasion, while its inactivation could play a role in tumor development." (PMID 30886832, 2019). "However, upregulated RhoA expression is associated with tumor progression in ovarian, gastric, and testicular cancer cells." (PMID 30872677, 2019). "Furthermore, tumor invasion- and metastasis-associated proteins, such as RhoA, Ras, MKK7 and MEKK3, were found to be inhibited by flaccidoxide-13-acetate treatment." (PMID 29280977, 2017). "Since the capability for anchorage-independent growth and resistance against anoikis may be a prerequisite for the survival of tumor cells during metastasis, this RHOA mutation may provide a selective advantage for metastasis." (PMID 26811494, 2016). "Interestingly, overexpression of these targets, such as matrix metalloproteinase-9, ras homolog family member A and vasodilator-stimulated phosphoprotein, have been demonstrated to be associated with tumor migration and invasion." (PMID 27474169, 2016). "In contrast, mutated RHOA interacts with other cellular proteins to promote morphological changes and cell migration, functions that may be important for tumor growth." (PMID 26267324, 2015). "Indeed, RhoA and RhoC have been shown to be involved in different stages of tumor progression such as loss of cell polarity and cell junctions, intravasation and vascularization." (PMID 24587105, 2014). "PKA-mediated phosphorylation at Ser304 has been shown to promote the translocation of p75NTR to lipid rafts and to regulate the downstream signals of p75NTR, including the inactivation of RhoA, which has been implicated in the process of tumor cell invasion and metastasis." (PMID 23833645, 2013). "It has been acknowledged that PKA may inhibit RhoA signaling, which has been implicated in the process of tumor cell invasion and metastasis." (PMID 23833645, 2013). "Whether Rgnef signaling connections linked to tumor progression involve RhoA or RhoC remain unknown." (PMID 22649559, 2012). "In addition, several proteins such as enolase, vimentin, peroxiredoxin 5, Hsp 70, periostin precursor, RhoA, cathepsin D preproprotein, and annexin 1 were found to be associated with the tumor responses to treatment within each subtype." (PMID 22110952, 2011). "In addition, mutations of the K-ras, rhoA, B and C genes were studied in the same series of tumour tissues to correlate with rho gene expressions." (PMID 9459160, 1998). "The increase in RhoA and Rac1 levels observed after mechanical stretching in clinical samples supports the hypothesis that these markers are closely associated with the mechanical environment of the tumor." (PMID 39887960, 2025). "As a key regulator of cytoskeletal dynamics, RHOA inhibition could affect both immune cells–where it modulates T–cell activation and migration–and cancer–associated fibroblasts (CAFs), which rely on RHOA for matrix remodelling and tumour invasion." (PMID 41362935, 2025). "The recent deciphering of activating or inactivating mutations affecting the RHOA GTPase and/or its complexes networks in hematological cancers strongly support the notion that, similarly to solid tumors, RHOA can exert pro- or anti-tumorigenic functions depending on the cell context and tumor type." (PMID 36766776, 2023). "Genomic analysis and flow cytometry for tumor-infiltrating lymphocytes (TILs) revealed a subset with low expression of genes associated with immune response and high-frequency infiltration of regulatory T lymphocytes (Treg), and almost half of the subset had RHOA Y42C mutation." (PMID 35751736, 2022).
tumor (continued). "However, in tumor cells, epithelial–mesenchymal transition, which is a typical morphological change associated with the loss of cell polarity, often occurs together with RhoA activation." (PMID 29659486, 2018). "N-WASP might also cause the upregulation of RhoA, as observed in almost all our tumour cases." (PMID 29976164, 2018). "In addition, we found that PAD2 depletion suppresses the expression of the cytoskeletal regulatory proteins RhoA, Rac1, and Cdc42 and also promotes a mesenchymal to epithelial-like transition in tumor cells with an associated increase in the cell adhesion marker, E-cadherin." (PMID 28549415, 2017). "Here, RhoA-mediated mesenchymal-to-amoeboid transition has been implicated, indicating a qualitative shift in cell migration characterized by cell rounding, single cell invasion and a squeezing movement style, leading to tissue invasion and tumor dissemination." (PMID 27246245, 2016). "The cytoskeleton protein, anillin (ANLN), has been reported to contribute to various tumor growth by participating in cytokinesis via RhoA signaling." (PMID 41513610, 2026). "At the molecular level, Western blot showed that RSPO4 expression led to reduced phosphorylation of RhoA (Ser188) in tumor cells." (PMID 41522353, 2026). "The upregulation of RhoA and Rac1 in response to mechanical stress highlights the critical role of the tumor microenvironment in cancer progression." (PMID 39887960, 2025). "Current studies indicate that ANLN promotes tumor progression by regulating the cell cycle, cytoskeletal dynamics, and multiple oncogenic pathways, including RhoA and PI3K/AKT." (PMID 41573677, 2025). "The activated RHOA pathway is pivotal for tumour cell proliferation, cytoskeletal reorganisation, angiogenesis, and metastasis." (PMID 41362935, 2025). "In tumor cells, a key driver of amoeboid migration that acts downstream of RAS/MEK/ERK is RhoA, as a small GTPase that activates ROCK (Rho-associated protein kinase)." (PMID 41511306, 2025). "In contrast, inhibiting RhoA reverses this process, promoting M1 macrophage polarization, which has anti-tumor properties." (PMID 40330466, 2025). "GNA13 promotes tumor cell invasion and metastasis by activating the RhoA/ROCK signaling pathway and the GPCR, BC regulation by Stathmin1, and Estrogen Pathway." (PMID 40149317, 2025). "PYK2 in exosomes activates the RhoA signaling pathway within OS cells and promotes the generation of M2-type macrophages, which are known to support tumor metastasis, thereby accelerating OS metastasis to the lungs." (PMID 40028322, 2025). "Flow cytometry analysis enabled the precise quantification of RhoA and Rac1 at the single‐cell level, offering a detailed, high‐resolution view of the cellular heterogeneity within tumor populations." (PMID 39887960, 2025). "This pattern suggests that RhoA expression not only correlates with tumor progression but also intensifies as the cancer advances, reflecting the increasingly aggressive and resilient nature of higher‐stage tumors." (PMID 39887960, 2025). "Overall, mutated genes identified in the tumor‐enriched cohort were concordant, with recurrent variants identified in TET2, DNMT3A, RHOA, IDH2, and TET3." (PMID 40510016, 2025). "C3 exotoxin from Clostridium botulinum, Grincamycin B, and Riboprine (N6-isoprenyladenosine) inhibit RhoA activity, in turn suppressing tumor growth and invasion [3,]." (PMID 40746849, 2025). "During our investigation of the function of GNAQ in promoting NKTCL, we unexpectedly identified the tumour–suppressor gene RHOA as a potential player." (PMID 41362935, 2025). "These mutations lock RHOA in its GTP-bound state, leading to sustained signaling that drives tumor progression." (PMID 41291745, 2025).
tumor (continued). "Immunoblotting revealed varying levels of endogenous expression of total LARG, pLARG S1288 and RhoA between the tumor samples." (PMID 41338458, 2025). "Although RHOA upregulation occurs in GC and promotes tumor invasiveness, little is known regarding its function in hypoxic GECs." (PMID 40600795, 2025). "PYK2 in tumor exosomes can also trigger STAT3 activation in macrophages by activating the RhoA pathway in OS cells." (PMID 40028322, 2025). "For endogenous lactylation detection in tumor tissues, prior immunoprecipitation using RHOA antibody was required to overcome cross-reactivity from conserved K118/K162 sites across RHO family proteins." (PMID 41291745, 2025). "Nude mice orthotopically injected with shGNAQ YT cells presented greater tumour burdens than control mice did, while RHOA overexpression abrogated the tumour growth–promoting effects of shGNAQ." (PMID 41362935, 2025). "Collectively, our findings identify polycystin‐1 as a mechanosensor of collagen and ECM stiffness that modulates tumor cell migration via the Daam1/RhoA/YAP signaling cascade." (PMID 40789101, 2025). "Clinical data analysis showed that abnormally high expression of USP9X was closely associated with high tumor grade and poor survival rate, and USP9X was positively correlated with RHOA protein expression levels." (PMID 41291745, 2025). "Tumor wet weight (1569.9 ± 595.5 vs. 636.5 ± 288.9 mg, p = 0.009) and activation of RhoA and FAK were decreased in the EphA2-knockdown group (p < 0.05 for all)." (PMID 41440001, 2025). "In this study, the occurrence of metastasis was reduced by inhibiting the RhoA-ROCK signaling pathway to reduce the mechanosensitivity of tumor cells." (PMID 40655948, 2025). "GIPC1 and DAB2IP, which regulate PI3K–AKT, ERK, and RhoA pathways, are predominantly reduced in dedifferentiated tumor subtypes, consistent with the release of growth-promoting signaling." (PMID 41374987, 2025). "Our research opens the avenue for exploring the time-resolved responses of RHOA to hypoxia in GC, potentially uncovering novel therapeutic targets for tumor development." (PMID 40600795, 2025). "Our studies reveal a previously uncharacterised role of Mdmx in cell invasion through the RhoA GTPase, providing mechanistic insights into the emerging tumour suppressor functions of Mdmx." (PMID 39404389, 2024). "RhoA/ROCK activation also induces epithelial-to-mesenchymal transition (EMT) that exerts a vital role in tumor cell metastasis, especially for OC cells." (PMID 39104601, 2024). "The Rho family acts as a regulatory factor to mediate cell migration, among which RhoA is a key member involved in regulating tumor cell invasion and metastasis by affecting the cellular cytoskeleton." (PMID 38528546, 2024). "Binding of LN-511 to integrin receptors triggers the formation of FAK, PI3K, ERK, and RhoA signaling pathways that drive tumor cell migration and invasion." (PMID 38287441, 2024). "miR‐200b's modulation of ARHGAP18 is observed to activate RhoA, leading to enhanced formation of adhesion sites and actin stress fibres, ultimately reducing tumour cell migration and metastatic potential." (PMID 39075640, 2024). "The data on the anti-invasive role of Mdmx through control of RhoA now propose a molecular pathway for the reported tumour-suppressive functions of Mdmx." (PMID 39404389, 2024). "These tumour-suppressive functions of Mdmx were mapped within the Zn finger domain, which we identify as the domain required for the binding of Mdmx to RhoA." (PMID 39404389, 2024). "The intratumoural injection of p190RhoGAP siRNA in 451Lu tumours suppressed the expression of p190RhoGAP and induced the activity of RhoA and PTEN whereas suppressed the phosphorylation of Akt." (PMID 38182748, 2024). "The RhoA/ROCK pathway is critical for metastasis of tumor cells via stimulating the phosphorylation of myosin light chain (MLC), leading to the assembly of actin." (PMID 39104601, 2024).